Y_RNA (Y RNA )
Gene: Miscellaneous RNA gene on chromosome 1 (31,503,631 to 31,503,744, reverse strand). Ensembl gene ENSG00000265961.
Homologues: Orthologues: chimpanzee Y_RNA (99% identical), macaque Y_RNA (89% identical). Paralogues in human: Y_RNA (86% identical), Y_RNA (85% identical), Y_RNA (84% identical), Y_RNA (83% identical), Y_RNA (82% identical), RNY1P5 (81% identical), Y_RNA (81% identical), RNY1 (80% identical), Y_RNA (80% identical), Y_RNA (79% identical), RNY1P8 (78% identical), Y_RNA (78% identical), and 93 more.